CRP (C-reactive protein)
Diseases named in the same sentence as CRP in open-access papers (continued):
Sharing a sentence is not in itself a finding about the gene and the disease.
rectal cancer (continued). "Our findings demonstrate that increased CRP levels and CRP-based ratios serve as significant predictors of postoperative complications in rectal cancer surgery." (PMID 39598263, 2024). "Multiple studies have investigated the association between CRP levels, CRP ratios, the CCI, and hospitalization costs in identifying postoperative complications following rectal cancer surgery." (PMID 39598263, 2024). "The CRP/Albumin Ratio (CAR) after rectal cancer surgery has been found to be a reliable indicator of early problems." (PMID 39598263, 2024). "This study enhances existing findings by concentrating on rectal cancer surgery, thereby affirming the predictive value of CRP within this specific surgical setting." (PMID 39598263, 2024). "To summarize, CRP is a valuable and dynamic biomarker for predicting and treating postoperative problems in rectal cancer surgery." (PMID 39598263, 2024). "Rectal cancer surgery complications can be detected immediately with postoperative C-reactive protein (CRP) monitoring." (PMID 39598263, 2024). "Postoperative complications after rectal cancer surgery can be detected early using CRP and its ratios." (PMID 39598263, 2024). "There were 536 rectal cancer patients previously treated with chemotherapy, of whom the CRP levels of 145 were examined." (PMID 38074681, 2023). "The results showed that the CRP levels were significantly higher in rectal cancer patients with CVD than those in patients with CVD." (PMID 38074681, 2023). "In this study, we conducted a retrospective study to investigate the association between CRP and CVD in patients with rectal cancer." (PMID 38074681, 2023). "Afterwards, we analyzed CRP levels among nine categories of CVD in rectal cancer patients with CVD and in patients with CVD, respectively." (PMID 38074681, 2023). "Univariable and multivariable logistic regression analysis of the association between CRP and CVD in patients with rectal cancer." (PMID 38074681, 2023). "We also demonstrated that chemotherapy had an impact on CRP levels, as evidenced by elevated levels of CRP in rectal cancer patients treated with chemotherapy." (PMID 38074681, 2023). "We further analyzed differences in levels of CRP among rectal cancer patients to evaluate the impact of chemotherapy on CRP." (PMID 38074681, 2023). "Another RCT found that ω-3 FAs capsules significantly reduced the Glasgow Prognostic Score (GPS), a prognostic cancer marker based on inflammation composed of CRP and albumin, in patients with local advanced rectal cancer receiving neoadjuvant radiotherapy." (PMID 37686570, 2023). "To evaluate the influence of chemotherapy on CRP levels, we compared CRP levels of patients with rectal cancer before and after chemotherapy." (PMID 38074681, 2023). "Recently, the low levels of the lymphocyte–CRP ratio found in rectal cancer patients before nCRT were considered an independent prognostic factor for both recurrence-free survival and OS." (PMID 35158759, 2022). "We observed that the minor alleles of two CRP SNPs (rs1205 and rs1130864) as well as the genetic CRP-score were associated with higher CRC risk, slightly more pronounced for colon compared to rectal cancer." (PMID 35739525, 2022). "The ability of CRP to predict AL in the first week after anterior resection for rectal cancer is significant." (PMID 36105895, 2022). "Hemoglobin (Hg), C-reactive protein (CRP), platelets, carcinoembryonic antigen, carbohydrate antigen 19.9 levels, and neutrophil/lymphocyte ratio were obtained from 171 rectal cancer patients before nCRT." (PMID 35158759, 2022). "Elevated CRP level was identified as an independently significant predictive factor for poor disease-free survival in patients with rectal cancer treated by chemoradiotherapy." (PMID 34321074, 2021). "A recently published study analyzed 86 patients with rectal cancer who received preoperative chemoradiotherapy and they verified lymphocyte-CRP ratio as a predictive biomarker." (PMID 34321074, 2021).
rectal cancer (continued). "They found that serum uric acid concentration was correlated with the presence of C-reactive protein and carcinoembryonic antigen in patients with rectal cancer and the presence of an inflammatory response." (PMID 33005687, 2020). "In our study, the pre-treatment plasma CRP level was identified as a significant prognostic factor in rectal cancer patients treated with nRCT." (PMID 33023215, 2020). "In patients with locally advanced rectal cancer treated with nRCT, data on the prognostic significance of the pre-treatment plasma CRP level are very limited." (PMID 33023215, 2020). "High TIMP-1 levels indicated poor survival among patients with rectal cancer (HR 1.95, 95% CI 1.17–3.26, P = 0.011), with left-sided tumor (HR 1.95, 95% CI 1.27–3.00, P = 0.002), and with low CRP (HR 1.59, 95% CI 1.05–2.42, P = 0.029)." (PMID 29929486, 2018). "To see whether other non-coding SNP sites of CRP are mutated in tumors, we determined the genotypes of 3 CRP common SNPs (rs7553007, rs1205, and rs3093077) together with 21 additional SNPs in 141 tumor/normal sample pairs of 5 cancer types, i.e. gastric, lung, esophagus, colon and rectal cancers." (PMID 25025473, 2014). "Serum TIMP-1 levels were found to be significantly increased in patients with preoperative CRP>12 mg/L and in those who died from rectal cancer or had cT4 tumours." (PMID 23801910, 2013). "Serum TIMP-1 levels were found to be significantly increased in patients with preoperative CRP>12 mg/L and in those who died from rectal cancer and were marginally increased in patients who had cT4 tumours." (PMID 23801910, 2013). "Hoek and colleagues suggest that the low prevalence of AL might have implications for the NPV of CRP in detecting leakage after rectal cancer surgery." (PMID 39712676, 2024). "It was suggested that monitoring CRP levels might provide new clues and a means for assessing CVD risk in patients with rectal cancer." (PMID 38074681, 2023). "In our study, subgroup analyses by gender in rectal cancer patients found an association between CRP levels and the risk of CVD only in men, whereas no such association was observed in women." (PMID 38074681, 2023). "Association between CRP and CVD in patients with rectal cancer after propensity score matching." (PMID 38074681, 2023). "This study aimed to investigate the association between increased C-reactive protein (CRP) and cardiovascular disease (CVD) in individuals with rectal cancer, as well as to understand the effect of chemotherapy for cancer on increasing CRP and its underlying mechanisms." (PMID 38074681, 2023). "In conclusion, our findings indicated that increased CRP levels following chemotherapy profoundly impacted CVD events in individuals with rectal cancer, and may be beneficial in promoting CVD prediction in clinical practice." (PMID 38074681, 2023). "Furthermore, a comparison of CRP levels before and after chemotherapy revealed a significant increase among rectal cancers post-treatment (p < 0.001)." (PMID 38074681, 2023). "A significant association between increased CRP and CVD events was observed in rectal cancer patients (p < 0.01), and it significantly improved the classification performance of the CVD predictive model in the AUC (0.724 vs 0.707) and NRI (0.069, 95% CI 0.05-0.14)." (PMID 38074681, 2023). "The positive association with pre-diagnostic CRP was observed for colon but not for rectal cancer, and among men but not women." (PMID 35739525, 2022). "The findings suggest that CRP level shows prognostic significance in rectal cancer patients." (PMID 34321074, 2021). "However, only a few studies have investigated the prognostic significance of the plasma CRP level in rectal cancer." (PMID 33023215, 2020).
rectal cancer (continued). "In view of the limitations of this study, our results have to be interpreted cautiously until validated in additional prospective large-scale studies before firm conclusions about the role of the pre-treatment CRP level for prognosis in patients with locally advanced rectal cancer can be drawn." (PMID 33023215, 2020). "Beside CRP, other inflammation-related parameters, such as white blood cell count, neutrophil/lymphocyte ratio, or erythrocyte sedimentation rate, are potential biomarkers for outcome in rectal cancer patients." (PMID 33023215, 2020). "When analysing the association between established clinicopathological parameters and TIMP-1, we found elevated TIMP-1 levels in patients with higher cT-stage and those who died from rectal cancer or had increased CRP before the start of the preoperative treatment." (PMID 23801910, 2013). "However, in individuals with rectal cancer, no data are available verifying the association between CRP and CVD." (PMID 38074681, 2023). "In the European Prospective Investigation into Cancer and Nutrition (EPIC), we previously observed that elevated circulating CRP concentrations were associated with a higher risk of colon but not rectal cancer and a higher risk of colon cancer was particularly observed in men but not in women." (PMID 35739525, 2022). "Thus, to find clinically relevant biomarkers of response to nCRT in rectal cancer patients, reinforce the results here presented, and better understand how CRP levels correlate with patient initial inflammatory status, we are now conducting a similar, but prospective, clinical study." (PMID 35158759, 2022). "Unlike our results, Buijsen, who investigated various pretreatment biomarkers as predictive factors for tumor response after nCRT in rectal cancer patients, did not detect a significant association between the pretreatment CRP level and tumor response after nCRT." (PMID 35158759, 2022). "In conclusion, early postoperative measurement of CRP on POD1 serves as a valuable and independent biomarker for predicting complications following RARS for rectal cancer." (PMID 40877485, 2025). "RALS for rectal cancer provided superior outcomes to CLS in terms of the bleeding amount, postoperative CRP levels, and postoperative hospital stay." (PMID 40397199, 2025). "This research assesses the predictive significance of C-reactive protein (CRP) levels and CRP ratios in the early identification of postoperative complications after rectal cancer surgery." (PMID 39598263, 2024). "Forinstance, recently published data by Aires and colleagues found that lower expression of CRP was an independent predictor of improved response to chemoradiotherapy (CRT) and survival for locally advanced rectal cancer patients." (PMID 36673123, 2023). "Then, in patients with rectal cancer, the relationship between increased CRP and CVD attributes was summarized, and the impact of chemotherapy on CRP levels was qualitatively assessed." (PMID 38074681, 2023). "Several studies have confirmed that C-reactive protein (CRP) and neutrophil-to-lymphocyte ratio (NLR) are predictive markers for treatment response and oncological outcomes in rectal cancer patients." (PMID 36832166, 2023). "To further identify the relationship between CRP and CVD in patients with rectal cancer, we conducted a univariate logistic regression analysis." (PMID 38074681, 2023). "CRP is extensively used in clinical practice as a marker of inflammation, while the management of CRP and CVD in individuals with rectal cancer is frequently disregarded." (PMID 38074681, 2023). "In this retrospective cohort study, the added value of CRP-guided CT imaging was evaluated for the diagnosis and subsequent management of AL after TME for rectal cancer in a cohort with highly selective diversion." (PMID 36002771, 2022). "We focused on the lymphocyte count/C-reactive protein ratio (LCR) and its usefulness in predicting short- and long-term outcomes after rectal cancer surgery." (PMID 36229569, 2022).
rectal cancer (continued). "Multivariate analysis using a Cox proportional hazards model showed that CRP was an independent predictor of DFS (Hazard Ratio (HR) = 5.481; 95% CI 1.542–19.485) and OS (HR = 6.096; 95% CI 1.267–29.323) in patients with rectal cancer treated with nCRT." (PMID 35158759, 2022). "For rectal cancer, statistical significance was demonstrated for CEA, CRP, and CCR3 (p = 0.003; p < 0.001; p = 0.012, respectively)." (PMID 34204490, 2021). "An increased pre-treatment plasma CRP level seems to represent an independent prognostic factor for RFS, LC, MFS, and OS in rectal cancer patients treated with nRCT." (PMID 33023215, 2020). "Nonetheless, even considering these limitations, our data indicate that a high plasma CRP level is an independent prognostic factor for RFS, LC, MFS, and OS in locally advanced rectal cancer patients." (PMID 33023215, 2020). "Some studies have observed that serum UA levels are positively correlated with C-reactive protein (CRP) and carcinoembryonic antigen (CEA) in patients with metastasis, and increased serum UA may predict metastasis in patients with rectal cancer." (PMID 37646984, 2024). "The present study identified the relationship between CRP and CVD in patients with rectal cancer." (PMID 38074681, 2023). "To recognize whether CVD in rectal cancer patients was distinct from that in CVD patients, we compared the CRP levels between the two groups." (PMID 38074681, 2023). "Previously, various studies have shown significant associations between blood-based inflammatory parameters such as C-reactive protein (CRP), the neutrophil-to-lymphocyte ratio (NLR), and the platelet-to-lymphocyte ratio (PLR) and prognosis in several cancer entities, including rectal cancer." (PMID 34070592, 2021). "Among irradiated rectal cancer patients, CRP (divided by ten) level was not a predictor of overall (HR 0.95, 95% CI 0.83–1.08) nor cancer-specific survival (HR 0.83, 95% CI 0.55–1.25)." (PMID 32316975, 2020). "In contrast to the results of two studies, CRP was not an independent predictor of survival among irradiated rectal cancer patients in this study." (PMID 32316975, 2020). "In our hospital the CRP level is not evaluated during the preoperative work-up of patients with rectal cancer not suspected to have infection or inflammation." (PMID 30718566, 2019). "In conclusion, anastomotic leakage, with its accompanying CRP increase, might not be a driver for recurrence and long-term death after anterior resection for rectal cancer." (PMID 39621059, 2024). "However, data on the prognostic role of the pre-treatment CRP level in non-metastatic rectal cancer are limited and derived from studies analyzing relatively small numbers of patients." (PMID 33023215, 2020). "Infiltration of the tumor stroma by T-regulatory FOXP3+ cells showed a significantly negative low correlation to CRP (Spearman’s rho –0.18, 95% CI from –0.32 to –0.05 for all non-irradiated and –0.24, 95% CI from –0.42 to –0.05 for non-irradiated rectal cancers." (PMID 32316975, 2020).
AIDS (51 papers, 2008 to 2026). A syndrome resulting from the acquired deficiency of cellular immunity caused by the human immunodeficiency virus (HIV). "We also found that immunosuppressant use, alteration of blood cell counts, and CRP are important mediators for the majority of the observed associations between AIDs and cancer." (PMID 40386413, 2025). "Immunosuppressant use, alteration of peripheral blood counts, and CRP were identified as likely mediators of the associations between AIDs at baseline and cancer." (PMID 40386413, 2025). "We have observed significant association between elevated levels of IL-6 and CRP among the AIDS Linked to the Intra Venous Experience (ALIVE) study participants, a large cohort of injection drug users (IDUs) with or at high risk for HIV infection." (PMID 29097998, 2017). "A recent retrospective case-control study in HIV+ patients demonstrated that higher pre-ART plasma levels of IL-6, D-dimer and CRP are associated with increased risk of AIDS events, IRIS or death." (PMID 23691062, 2013). "On the other hand, there are studies that reported IL-6 to be strongly associated to non AIDS events compared to CRP during HIV infection, therefore variability observed in our study may be due to chance." (PMID 31331321, 2019). "For example, in a study of ART-naïve patients from multiple sites within the United States, individuals with pre-ART CRP greater than the median within the study population were more likely to experience AIDS events and death from all causes within the first year of treatment." (PMID 25719208, 2015). "Understanding the cause of TNFR p55, IFN-γ and CRP elevation may be useful in development of interventions to reduce mortality in AIDS patients with chronic diarrhoea in Africa." (PMID 19014537, 2008). "HIV infection, AIDS, hematological malignancy, non-Hodgkin lymphoma, solid tumor, metastatic solid tumor, Charlson Comorbidity Index, previous chemotherapy, previous radiotherapy, increasing serum CRP values, and bilateral ground-glass opacities were associated with PJP in univariable analysis." (PMID 37620828, 2023). "Notably, a recent diagnostic accuracy study conducted in 2 Ugandan HIV/AIDS clinics showed that point-of-care CRP screening of HIV-infected people with CD4 counts <351 cells per μL who were initiating antiretroviral therapy yielded 89% sensitivity and 72% specificity for culture confirmed TB." (PMID 30990820, 2019). "Laboratory serological markers of AIDs are C reactive protein (CRP) and serum amyloid A (SAA) protein." (PMID 36096831, 2022). "Independent predictors of pre-frailty/frailty in the multivariable analysis differ in men (VACS index, C-reactive protein [CRP], and falls) and women (CRP, AIDS, and menopause)." (PMID 31071105, 2019). "CRP (OR 9.29; CI 95% 2.0–43.07; p 0.004); AIDS (OR 3.94; CI 95% 1.21–12.82; p 0.023), and menopause (OR 3.53; CI 95% 1.28–9.67; p 0.014) in women." (PMID 31071105, 2019). "And Kyn/Trp ratio (95%CI 0.673–0.949, P = 0.002), D-dimer (95%CI 0.612–0.899, P = 0.010) and CRP (95%CI 0.674–0.977, P = 0.001) had much higher AUC for predicting death of AIDS-PCP patients." (PMID 30832615, 2019). "The loss of Th17 cells correlated inversely with local and systemic T-cell activation and CRP and HA plasma levels, which are increased in treatment-naïve CHI and associated with an increased risk of developing AIDS." (PMID 25503054, 2014). "The present study shows that all HIV/AIDS patients had elevated hs-CRP levels and antibodies against oxidized LDL cholesterol in terms of oxidative stress, proinflammatory and chronic inflammation." (PMID 22347662, 2011). "Given the strong association of CRP with cardiovascular disease, these findings emphasize that HIV prevention and ART initiation during primary infection could diminish non-AIDS events." (PMID 37461626, 2023). "Kyn/Trp ratio, D-dimer and CRP showed much higher AUC for predicting death of AIDS-PCP patients." (PMID 30832615, 2019).